SLC30A9 (solute carrier family 30 member 9)
Diseases named in the same sentence as SLC30A9 in open-access papers:
SLC30A9 is named in the same sentence as 34 diseases in open-access papers, as found by Europe PMC text mining. Sharing a sentence is not in itself a finding about the gene and the disease. The quoted sentences say what the papers report.
Intellectual disability (5 papers, 2017 to 2025). "A single mutation in SLC30A9 was recently found to be associated with an autosomal recessive cerebro-renal syndrome, which manifests as neurological deterioration, intellectual disability, ataxia, camptocormia, oculomotor apraxia, and nephropathy." (PMID 34687432, 2022).
breast carcinoma (4 papers, 2015 to 2026). "Analysis of differential expression levels highlighted CLDND1, PLEKHA2, ACSL3, SLC30A9, MSN, CALM3 and PRKAR1A as potential regulators of breast cancer cell survival since they were affected by PKCδ siRNA in all cell lines." (PMID 26083392, 2015).
prostate carcinoma (4 papers, 2019 to 2024). A carcinoma that arises from epithelial cells of the prostate gland. "Based on the Oncomine database records, the expression of Zn-exporter genes SLC30A1, SLC30A9, and SLC30A10 are upregulated, and SLC30A5 and SLC30A6 are downregulated in prostate cancer compared to BPH." (PMID 36551962, 2022). "Deregulation of SLC30A9 expression was also reported for hepatocellular carcinoma (HCC) and prostate cancer (PCa)." (PMID 34687432, 2022).
Zinc deficiency (4 papers, 2015 to 2025). A deficiency of the essential metal Zinc; an essential cofactor for many enzymes. "A linear regression was performed to reveal the relationship between the zinc deficiency state and H2 of SLC30A9 in corresponding populations." (PMID 25927708, 2015). "Finally, to explore the possible reasons underlying this interesting distribution pattern of haplotypes in SLC30A9, we performed a correlation between the haplotype frequency of H2 in each population and the corresponding zinc deficiency status." (PMID 25927708, 2015).
Birk-Landau-Perez syndrome (3 papers, 2023 to 2024). "A few years ago, it was first reported that SLC30A9 (ZnT9) mutations in humans cause a novel cerebro-renal syndrome called Birk–Landau–Perez Syndrome." (PMID 39158587, 2024). "Birk-Landau-Perez syndrome is a genetic disorder caused by biallelic pathogenic variants in SLC30A9 presenting with a complex movement disorder, developmental regression, oculomotor abnormalities, and renal impairment." (PMID 37041080, 2023). "Birk–Landau–Perez syndrome (BILAPES) is an autosomal recessive cerebro-renal syndrome associated with genetic defects in the SLC30A9 gene, initially reported in 2017 in six individuals belonging to a large Bedouin kindred." (PMID 37576556, 2023). "A distinctive autosomal recessive cerebro-renal syndrome, designated as Birk–Landau–Perez syndrome (BILAPES) (OMIM# 617595), has been reported to be associated with biallelic pathogenic variants in SLC30A9." (PMID 37576556, 2023).
hepatocellular carcinoma (3 papers, 2020 to 2022). A malignant tumor that arises from hepatocytes. "SLC30A9 expression is significantly higher in hepatocellular carcinoma tissues than adjacent non-cancerous tissues, but is not correlated with survival in hepatocellular carcinoma patients." (PMID 33110097, 2020).
cervical cancer (2 papers, 2022 to 2025). A primary or metastatic malignant neoplasm involving the cervix. "We investigated the expression, function, and underlying mechanisms of SLC30A9 in the context of cervical cancer." (PMID 41419464, 2025). "We next conducted an analysis of the possible molecular mechanism underlying the elevated expression of SLC30A9 in cervical cancer." (PMID 41419464, 2025). "These new findings from independent datasets provide more robust evidence for the prognostic significance of SLC30A9 in cervical cancer and its potential association with tumor progression and HPV infection." (PMID 41419464, 2025). "Therefore, dysregulated mitochondrial function represents an important mechanism underlying the SLC30A9-silencing-induced anti-cervical cancer cell activity." (PMID 41419464, 2025). "Our findings indicate that silencing or knockout the zinc transporter SLC30A9 in pCCa-1 cervical cancer cells leads to a significant increase in mitochondrial zinc (Zn 2+) levels, a result consistent with previous research." (PMID 41419464, 2025). "qRT-PCR analysis demonstrated a significant upregulation of SLC30A9 mRNA levels in all three cervical cancer cell types." (PMID 41419464, 2025). "Conversely, overexpression of SLC30A9 in cervical cancer cells demonstrated enhanced mitochondrial complex I activity, increased ATP production, and augmented cellular proliferation and migration." (PMID 41419464, 2025). "In conclusion, our findings indicate that SLC30A9 overexpression promotes the malignant phenotype of cervical cancer cells." (PMID 41419464, 2025). "To explore the functional impact of SLC30A9 on the in vivo proliferation of cervical cancer cells, we developed subcutaneous xenograft models in nude mice using pCCa-1 cells that were engineered to express either shSLC30A9-S2 or a control shRNA (shC)." (PMID 41419464, 2025). "Our findings provide robust evidence for SLC30A9 as a promising therapeutic target of cervical cancer, supported by a range of analyses." (PMID 41419464, 2025). "To assess the consistency of SLC30A9 silencing in cervical cancer cells, we introduced shSLC30A9-S2 into additional primary/immortalized cancer cells (pCCa-2, pCCa-3, and HeLa)." (PMID 41419464, 2025). "Silencing SLC30A9 via shRNA significantly impeded the viability, proliferation, cell cycle progression, and migratory capacity of primary/immortalized cervical cancer cells." (PMID 41419464, 2025). "Collectively, these results highlight the critical role of overexpressed SLC30A9 in maintaining mitochondrial hyperfunction in cervical cancer cells." (PMID 41419464, 2025). "Conversely, overexpression of SLC30A9 in various cervical cancer cells demonstrated enhanced mitochondrial complex I activity and ATP production." (PMID 41419464, 2025). "These possibilities provide a compelling framework for future investigations into this SLC30A9-mediated zinc-dependent regulatory axis in cervical cancer cells." (PMID 41419464, 2025). "Analyzing all twenty patient tissue Western blotting results, we found a significant upregulation of SLC30A9 protein in the cervical cancer tissues." (PMID 41419464, 2025). "In vivo studies showed that SLC30A9 knockdown led to a remarkable decrease in the growth of xenografts formed by primary cervical cancer cells." (PMID 41419464, 2025). "To further investigate the functional role of SLC30A9 in cervical cancer, we utilized the CRISPR/Cas9 gene editing technique to knock out (KO) SLC30A9 in cervical cancer cells." (PMID 41419464, 2025). "Elevated levels of SLC30A9 were observed in cervical cancer tissues from patients undergoing local treatment, as well as in several primary and established cervical cancer cells." (PMID 41419464, 2025). "To explore the impact of overexpressed SLC30A9 on the aggressive behaviors of cervical cancer cells, we utilized a strategy involving shRNA-mediated knockdown to inhibit SLC30A9 expression." (PMID 41419464, 2025).
cervical cancer (continued). "Subsequent siRNA-mediated knockdown in pCCa-1 cervical cancer cells targeting these factors revealed that only PRDM1 silencing substantially downregulated SLC30A9 mRNA expression." (PMID 41419464, 2025). "This elevated SLC30A9 expression was further corroborated in clinical specimens from local patients and across various established and primary cervical cancer cells." (PMID 41419464, 2025). "Silencing or knockout of PRDM1 resulted in a significant reduction in SLC30A9 promoter activity, as well as decreased SLC30A9 mRNA and protein levels in primary cervical cancer cells." (PMID 41419464, 2025). "qRT-PCR analysis demonstrated a significant reduction in SLC30A9 mRNA levels across all three cervical cancer cell types." (PMID 41419464, 2025). "Concomitantly, PRDM1 depletion resulted in decreased luciferase activity driven by the SLC30A9 promoter in primary cervical cancer cells, further supporting the role of PRDM1 in regulating SLC30A9 transcription." (PMID 41419464, 2025). "Ectopic SLC30A9 overexpression led to increased ATP levels in the cervical cancer cells, suggesting enhanced mitochondrial function." (PMID 41419464, 2025). "We transduced patient-derived primary human cervical cancer cells, identified as pCCa-1, with lentiviruses carrying two unique shRNA sequences directed against human SLC30A9 (shSLC30A9-S1 and shSLC30A9-S2)." (PMID 41419464, 2025). "The findings revealed that both SLC30A9 mRNA and protein levels were significantly increased in primary human cervical cancer cells (“pCCa-1,” “pCCa-2,” and “pCCa-3”, derived from three patients) and the immortalized HeLa cell line." (PMID 41419464, 2025). "Our findings strongly suggest that SLC30A9 overexpression plays a pivotal role in driving the hyperfunction of cervical cancer cells." (PMID 41419464, 2025). "PRDM1 silencing or KO led to a marked decrease in both SLC30A9 mRNA and protein expression levels in pCCa-1 primary cervical cancer cells, accompanied by a significant reduction in the luciferase activity of the SLC30A9’s promoter." (PMID 41419464, 2025). "Given its critical role in mitochondrial function, further investigation into SLC30A9’s involvement in cervical cancer pathogenesis is warranted." (PMID 41419464, 2025). "Chromatin immunoprecipitation (ChIP) assays confirmed increased PRDM1 binding to the SLC30A9 promoter region in cervical cancer tissues." (PMID 41419464, 2025). "We next aimed to investigate whether silencing SLC30A9, a zinc transporter within mitochondria, could impact mitochondrial functions in cervical cancer." (PMID 41419464, 2025). "Thus, SLC30A9 knockout demonstrated significant anti-cancer effects in primary cervical cancer cells." (PMID 41419464, 2025). "Additionally, the protein expression of SLC30A9 was markedly increased in the cervical cancer samples of four representative patients (Patients 1# to 4#)." (PMID 41419464, 2025). "Furthermore, immunohistochemistry (IHC) staining for Patients 1# to 2#’s tissue slides corroborated the pronounced increase in SLC30A9 protein levels in cervical cancer." (PMID 41419464, 2025). "The expression of SLC30A9 in human cervical cancer cells was also examined." (PMID 41419464, 2025). "Since SLC30A9 silencing or knocking out resulted in substantial anti-cancer effects in cervical cancer cells, we hypothesized that artificially overexpressing SLC30A9 could potentially promote malignant behaviors." (PMID 41419464, 2025). "Additionally, the CCK-8 assay revealed decreased cell viability in the SLC30A9-silenced cervical cancer cells." (PMID 41419464, 2025). "This study delves into the molecular mechanisms driving SLC30A9 overexpression in cervical cancer." (PMID 41419464, 2025). "The knockdown of SLC30A9 led to a considerable decrease in cell proliferation, as indicated by EdU incorporation, as well as impaired in vitro cell migration in both primary and immortalized cervical cancer cells." (PMID 41419464, 2025).
cervical cancer (continued). "We first investigated the expression of SLC30A9 in cervical cancer tissues from our local patients." (PMID 41419464, 2025). "Furthermore, both proliferation (measured by nuclear EdU incorporation) and migration (measured by “Transwell” assays) were elevated in both primary and immortalized cervical cancer cells following SLC30A9 overexpression." (PMID 41419464, 2025). "Thus, SLC30A9 silencing led to mitochondrial zinc accumulation in cervical cancer cells." (PMID 41419464, 2025). "Furthermore, ChIP analysis in human tissues, using two distant primer pairs (Primer Pair #1 and Primer Pair #2), demonstrated that the binding activity of PRDM1 to the SLC30A9 promoter region was significantly elevated in cervical cancer tissues compared to adjacent normal cervical tissues." (PMID 41419464, 2025). "Furthermore, SLC30A9 knockdown led to a remarkable decrease in the growth of cervical cancer xenografts, further emphasizing its potential as a valuable target for therapeutic strategies in the treatment of cervical cancer." (PMID 41419464, 2025). "Functional experiments demonstrated a significant reduction in SLC30A9 expression at both the mRNA and protein levels following PRDM1 silencing or KO in primary cervical cancer cells." (PMID 41419464, 2025). "Functional assays indicated that silencing SLC30A9 through shRNA or knockout using CRISPR/Cas9 method significantly hindered the viability, proliferation, and migratory abilities of cervical cancer cells, while simultaneously triggering apoptotic pathways." (PMID 41419464, 2025). "Importantly, ChIP assays revealed significantly increased binding of PRDM1 to the SLC30A9 promoter region in cervical cancer tissues, providing strong evidence for PRDM1’s direct involvement in upregulating SLC30A9 expression." (PMID 41419464, 2025). "SLC30A9 shRNA or knockout (via CRISPR/Cas9 method) significantly impeded the viability, proliferation, cell cycle progression and migration, and triggered apoptosis in cervical cancer cells." (PMID 41419464, 2025). "For tumor stages, SLC30A1, SLC30A7 and SLC30A10 groups significantly varied, whereas SLC30A2, SLC30A3, SLC30A4, SLC30A5, SLC30A6, SLC30A8 and SLC30A9 did not significantly differ in cervical carcinoma." (PMID 35154468, 2022). "However, the expression of SLC30A3, SLC30A4, SLC30A5, SLC30A6 and SLC30A9 genes in cervical cancer was not statistically significant compared to the corresponding paracancerous tissues." (PMID 35154468, 2022).
diffuse large B-cell lymphoma (2 papers, 2024). "NAT10 regulates solute carrier family 30 member 9 (SLC30A9)’s ac4C by modifying the adenosine monophosphate‐activated protein kinase/mammalian target of rapamycin signaling and promotes tumorigenesis in diffuse large B‐cell lymphoma." (PMID 39640362, 2024).
candidiasis (1 paper, 2022). Infection with the organism Candida. "In TWAS, four gene-disease associations were significant: SLC30A9 for otitis media (p = 8.06 × 10–7); LRP3 and WDR88 for candidiasis (p = 3.91 × 10–7 and p = 1.95 × 10–6); and AAMDC for hepatitis B (p = 1.51 × 10–6)." (PMID 36167494, 2022).
cervical squamous cell carcinoma (1 paper, 2025). A squamous cell carcinoma arising from the cervical epithelium. "Single-cell RNA sequencing analysis revealed a marked overexpression of SLC30A9 within the malignant epithelial cell population of cervical squamous cell carcinoma." (PMID 41419464, 2025). "Single-cell RNA sequencing revealed that SLC30A9 is markedly overexpressed in the malignant epithelial cell population of cervical squamous cell carcinoma." (PMID 41419464, 2025).
colorectal cancer (1 paper, 2020). A primary or metastatic malignant neoplasm that affects the colon or rectum. "SLC30A5-7 and 9 are significantly upregulated in colorectal cancer and SLC30A9 is involved in the canonical Wnt pathway." (PMID 33110097, 2020).
melanoma (1 paper, 2022). A malignant, usually aggressive tumor composed of atypical, neoplastic melanocytes. "SLC30A9 was mutated in 5 melanomas, 4 acral and 1 mucosal melanomas." (PMID 35706047, 2022). "SLC30A9 has not been previously implicated in melanoma or other cancer types, and additional evidence is needed to support its role as a driver gene." (PMID 35706047, 2022).
neuroblastoma (1 paper, 2017). Neuroblastoma (NB) is the most common solid, extracranial childhood tumor. "To test possible effects of the mutation on this activity of SLC30A9, we performed a dual-luciferase reporter assay in neuroblastoma (SH-SY5Y) cells transfected with either wild-type or mutant SLC30A9-overexpressing constructs [pCDNATM 3.1 (−) under control of the CMV promoter]." (PMID 28334855, 2017).
opioid dependence (1 paper, 2020). "Other studies have sought to separate opioid use from opioid dependence, and have thus far identified SNPs associated with SDCCAG8, SLC30A9, and BEND461." (PMID 32917924, 2020).
otitis media (1 paper, 2022). Inflammation of the anatomical structures of the middle ear, which is most often caused by an infectious process. "Another new observation was the association between genetically predicted expression of SLC30A9 and altered risk of otitis media." (PMID 36167494, 2022).
tumor (5 papers, 2016 to 2025). "Xenografts of pCCa-1 cells with silenced SLC30A9 (shSLC30A9-S2) also exhibited a marked reduction in Ki-67-positive cells compared to controls, signifying a substantial suppression of tumor growth in vivo." (PMID 41419464, 2025). "IHC staining in tumor sections further confirmed the effective knockdown of SLC30A9 protein expression within the shSLC30A9-S2 pCCa-1 xenografts." (PMID 41419464, 2025). "Although a minor increase in SLC30A9 expression was observed in muscle and macrophages (P > 0.05), statistical analysis confirmed that only the SLC30A9 expression within the epithelial cell population was significantly different between the tumor and para-tumoral tissues." (PMID 41419464, 2025). "The differential expression of SLC30A1, SLC30A5, SLC30A6, SLC30A9 and SLC30A10 was found to vary with tumor stage and grade and appears to be related mostly to early events in PCa development and progression." (PMID 27833104, 2016).
cancer (4 papers, 2022 to 2026). A tumor composed of atypical neoplastic, often pleomorphic cells that invade other tissues. "To confirm that the observed phenotypes above were specifically due to the loss of SLC30A9 and not off-target effects of the shRNA, we re-expressed an shRNA-resistant SLC30A9 cDNA (shR-SLC30A9) in the SLC30A9 knockdown pCCa-1 primary cancer cells (with shSLC30A9-S2)." (PMID 41419464, 2025). "We found telomere maintaining genes (TERF2, CTC1, and ACD), genes involved in zinc homeostasis (MTF1 and SLC30A9), transcription elongation factor complex components (ICE1, ICE2, ELL), and BCL6 corepressors (BCOR, BCORL1) uniquely invoked in TNBC cancers." (PMID 40700427, 2025).
infection (1 paper, 2022). The state of being infected such as from the introduction of a foreign agent such as serum, vaccine, antigenic substance or organism. "In vitro experiments suggested that SLC30A9 interacted with human influenza A virus; therefore, SLC30A9 might alter the risk of infection through its role in recognition and binding to pathogens." (PMID 36167494, 2022).
SLC30A9 also shares sentences with these, for which no sentence is quoted: Oculomotor apraxia (5 papers); Nephropathy (3); Camptocormia (2); movement disorder (2); Ataxia (1); colon cancer (1); developmental delay (1); dwarfism (1); genetic disorder (1); glioblastoma (1); hepatitis B (1); ischemia (1); Obesity (1); Renal insufficiency (1); Tremor (1); type 2 diabetes (1).